ADAMTS4 (ADAM metallopeptidase with thrombospondin type 1 motif 4)
Diseases named in the same sentence as ADAMTS4 in open-access papers (continued):
Sharing a sentence is not in itself a finding about the gene and the disease.
Arthritis (continued). "TIMP-3 may be a suitable therapeutic treatment for patients with arthritis to suppress not only innate inflammatory cytokines in arthritis but also ADAMTS4 and ADAMTS5." (PMID 25606593, 2014). "The basal (day 0) relative expression levels of the ADAMTSs further suggest that ADAMTS-4 and -9 may be important for cartilage homeostasis and support the hypothesis that in the bovine system, as in murine arthritis, ADAMTS-5 may be critically important." (PMID 16919164, 2006). "It is interesting to speculate that while ADAMTS5 is clearly the predominant aggrecanase responsible for acute aggrecanolysis in mouse cartilage in vitro and in different in vivo arthritis models, perhaps synovial ADAMTS4 plays a role in later stages of disease." (PMID 32059749, 2020). "However, whether ADAMTS4 or ADAMTS5 is predominately responsible for the cleavage of aggrecan in arthritis in humans remains controversial." (PMID 25606593, 2014). "The secreted metalloprotease ADAMTS4 and ADAMTS5 are responsible for the degradation of cartilage proteoglycan in arthritis." (PMID 39275306, 2024). "We will also provide an overview of past and current efforts to develop ADAMTS isotype-specific inhibitors that mainly target the aggrecanases ADAMTS4 and ADAMTS5 and are currently being pursued as potential disease-modifying arthritis drugs." (PMID 34268335, 2021). "It is well known that two major proteinases in the ADAMTS family are the capital enzymes contributed in the pathogenesis of arthritis: ADAMTS-4 and ADAMTS-5 called aggrecanase-1 and aggrecanase-2, respectively." (PMID 29137610, 2017). "Among the 19 members of ADAMTS family, ADAMTS-4 and ADAMTS-5 have received significant attention in the pathology of arthritic joint diseases because they are the most efficient aggrecanases in vitro." (PMID 28167976, 2017). "ADAMTS-4 and ADAMTS-5 were identified as the major cartilage aggrecanases in arthritis." (PMID 35140604, 2021). "The development of inhibitors for ADAMTS proteases is primarily focused on inhibiting ADAMTS4 and ADAMTS5 due to their prominent role in cartilage destruction in arthritis where both proteases degrade aggrecan, a major structural proteoglycan in the articular cartilage." (PMID 34268335, 2021). "Furthermore, a function study reported that the S100A8 stimulation in chondrocytes induces upregulation of mRNA levels of MMP-2, MMP-3, MMP-9, and MMP-13 and ADAMTS-4 and ADAMTS-5 in experimental murine arthritis, which is similar to our findings." (PMID 31815654, 2019). "Both ADAMTS4 and ADAMTS5 are responsible for aggrecan degradation in a human model of arthritis." (PMID 29757957, 2018). "However, evidence of their cooperative roles in cartilage degradation and common activation by inflammatory cytokines suggests that both ADAMTS4 and ADAMTS5 represent important therapeutic targets in arthritis." (PMID 25606593, 2014). "However, simultaneous inhibition of ADAMTS4 and ADAMTS5 may be desired in modifying arthritis progression." (PMID 34268335, 2021). "Studies with Adamts4-null mice disclosed that these mice were phenotypically normal and showed no protection against aggrecan degradation in inflammatory or surgically induced arthritis in mice, indicating that ADAMTS4 is not the main aggrecanase in mouse arthritis." (PMID 24213506, 2012). "Regulation of ADAMTS4 and ADAMTS5 gene expression by pro-inflammatory cytokines is not restricted to arthritis and was also described in the heart and the intervertebral disc." (PMID 34268335, 2021).
atherosclerosis (14 papers, 2013 to 2025). A disease characterized by the build-up of fatty material and calcium deposition in the arterial wall resulting in partial or complete occlusion of the arterial lumen. "Loss of ADAMTS4 is associated with increased collagen content and overall plaque stability in a mouse model of atherosclerosis." (PMID 35931792, 2022). "Our results demonstrate that loss of ADAMTS4 attenuated diet induced atherosclerosis with significantly reduced plaque burden in ApoE-deficient mice." (PMID 27491335, 2016). "In conclusion, removal of ADAMTS4 in ApoE-deficient mice reduces atherosclerosis and enhances plaque stability." (PMID 27491335, 2016). "In this work, we investigated the role of ADAMTS4 in diet induced atherosclerosis using apolipoprotein E deficient (ApoE−/−) and Adamts4 knockout mice." (PMID 27491335, 2016). "Nevertheless, whether increased ADAMTS4 is a consequence of atherosclerosis or ADAMTS4 has a causal role in atherogenesis remains unknown." (PMID 27491335, 2016). "Nevertheless, none of these studies revealed whether elevation in ADAMTS4 level is a consequence of atherosclerosis or ADAMTS4 has a causal role in atherogenesis." (PMID 27491335, 2016). "The extracellular matrix enzyme ADAMTS4 (A Disintegrin And Metalloproteinase with ThromboSpondin motifs 4) is strongly upregulated in cardiovascular diseases, including aneurysm and atherosclerosis, and therefore represents a promising in vivo target." (PMID 35606349, 2022). "Our data demonstrate that ADAMTS4 is not only a biomarker but also a contributor to atherosclerosis." (PMID 27491335, 2016). "Using high fat diet induced atherosclerosis in ApoE−/− mouse, we generated Adamts4 and ApoE double knockout mice (ApoE−/−Adamts4−/−)." (PMID 27491335, 2016). "To investigate if ADAMTS4 accumulation in plaques correlates with the progression of atherosclerosis in ApoE−/− mice, we analysed ADAMTS4 expression in plaques by immunohistochemistry (IHC)." (PMID 27491335, 2016). "The impact of ADAMTS4 removal on atherosclerosis is more striking in 18-weeks old mice compared to that of 12-weeks old mice." (PMID 27491335, 2016). "Although no changes in the plasma lipids between ApoE−/− and ApoE−/−Adamts4−/− mice were observed, removal of ADAMTS4 attenuates atherosclerosis." (PMID 27491335, 2016). "We next analysed the effect of Adamts4 knockout on high fat diet induced atherosclerosis in ApoE−/− mice." (PMID 27491335, 2016). "We found that ADAMTS4 is expressed in plaques and this expression increases as atherosclerosis progresses." (PMID 27491335, 2016). "To clarify the role of ADAMTS4 in atherosclerosis, we generated double knockout mice (ApoE−/−Adamts4−/−) by crossing Adamts4−/− mice with ApoE−/− mice (both in C57Bl/6J background)." (PMID 27491335, 2016). "The salient finding of the present study is that elimination of ADAMTS4 attenuates atherosclerotic plaque formation and reduces plaque vulnerability in high fat diet induced atherosclerosis of ApoE−/− mice." (PMID 27491335, 2016). "The attenuation of ADAMTS-4 expression by TGF-β is consistent with an anti-atherogenic plaque-stabilising role for TGF-β within atherosclerosis and backs up findings from a previous publication." (PMID 23859810, 2013). "Interestingly, in ADAMTS-4 knockout (KO) mice, a decrease in high fat diet-induced atherosclerosis and increased plaque stability were observed." (PMID 36142876, 2022). "Beyond aneurysms, an ADAMTS4-specific probe may also be useful for the early detection and the in vivo characterization of cardiovascular diseases, including atherosclerosis, as ADAMTS4 also plays a key role in these diseases." (PMID 35606349, 2022). "The mechanisms of action of ADAMTS-4 proposed in atherosclerosis might also be relevant in CKD; however, this remains to be elucidated." (PMID 35328201, 2022).
atherosclerosis (continued). "Alternatively, this discrepancy could stem from the fact that hemodialysis patients tend to have more comorbidities, especially cardiovascular diseases and atherosclerosis, which could be independent sources of elevated plasma ADAMTS-4." (PMID 35328201, 2022). "In this work, we experimentally clarified if ADAMTS4 plays a role in atherosclerosis." (PMID 27491335, 2016). "This work adds ADAMTS4 as another member of the ADAMTS family that contributes to atherosclerosis." (PMID 27491335, 2016). "We show that ADAMTS4 expression increases in plaques as atherosclerosis progresses in ApoE−/− mice." (PMID 27491335, 2016). "Hence, an obvious increase in plasma ADAMTS4 protein was also observed as atherosclerosis progresses in ApoE−/− mice from 12-weeks old to 18-weeks old." (PMID 27491335, 2016). "Thus, the possibility of using plasma ADAMTS4 as a biomarker for atherosclerosis warrants further exploration." (PMID 27491335, 2016). "Hence, removal of Adamts4 attenuates diet induced atherosclerosis in ApoE−/− mice." (PMID 27491335, 2016). "Elevated plasma levels of ADAMTS-4 have been consistently found in patients affected by coronary artery disease (CAD), atherosclerosis and TAAD." (PMID 33352066, 2020). "As inflammation is a major contributing factor in atherosclerosis progression and plaque instability, we next analysed if absence of ADAMTS4 influences the plasma inflammatory cytokines between 18 weeks old sex matched ApoE−/− and ApoE−/−Adamts4−/− mice." (PMID 27491335, 2016). "The increased expression of genes related to ECM degradation (e.g., Mmp14 and Adamts4) is consistent with previous findings showing that glucose-induced advanced glycation end products (RAGE) mediate modification of the components of the ECM and accelerate atherosclerosis under diabetic conditions." (PMID 35350534, 2022). "ADAMTS4 and ADAMTS1 may be involved in atherosclerotic plaque formation and stability, as both have been found to be highly expressed in macrophage-rich areas of human atherosclerosis plaques." (PMID 35606349, 2022).
disc degeneration (11 papers, 2005 to 2025). "This study also showed that larger quantities of ADAMTS4 are present in human NP and AF tissues derived from discs with a greater level of disc degeneration (grade 4) compared with those from discs with lower level of disc degeneration (grade 2)." (PMID 19889209, 2009). "Having established a basis for a functional excess of IL-1 in degenerate IVDs, we then investigated the role of IL-1 in the processes that characterize disc degeneration, namely, decreased matrix synthesis and increased production of MMPs and ADAMTS-4." (PMID 15987475, 2005). "Since metalloproteinases, particularly members of the ADAMTS and matrix metalloproteinase (MMP) families, are major contributors to aggrecan degradation and loss in disc degeneration, MMP-3, ADAMTS-4 and ADAMTS-5 message levels were also examined, as their suppression is essential for disc repair." (PMID 21787415, 2011). "For example, one study demonstrated that leptin promotes catabolic activity in rat NPCs by upregulating the expression of MMP‐1, MMP‐13, ADAMTS4, and ADAMTS5 via activation of the JAK2/STAT3 pathway, suggesting a mechanism contributing to disc degeneration." (PMID 41497807, 2025). "Our findings revealed that digoxin treatment inhibited the upregulation of MMP-13 and ADAMTS4/5 induced by TNF-α, leading to restoration of the expression of Col-2 and Aggrecan, indicating its potential role in inhibiting ECM degradation in disc degeneration." (PMID 37790932, 2023). "We showed in our previous studies with a larger range of patient population (78 patients with disc degeneration grade III, IV and V) higher levels of ADAMTS4 and lower levels of aggrecan in grade IV and V discs." (PMID 28207788, 2017). "Furthermore, they showed differences in overexpression of selective inflammatory and catabolic proteins (p<0.0001) similar to those found in human NP cells of different disc degeneration grades, such as IL-1β, TNF-α, ADAMTS-4, ADAMTS-5 and MMP-3." (PMID 31751427, 2019). "Unlike cartilage, in the nucleus pulposus (NP), both ADAMTS-4 and ADAMTS-5 expressions are elevated in human degenerative disc disease." (PMID 26438479, 2015).
Alzheimer disease (6 papers, 2019 to 2024). A progressive, neurodegenerative disease characterized by loss of function and death of nerve cells in several areas of the brain leading to loss of cognitive function such as memory and language. "Genetic variation in the gene encoding A Disintegrin and Metalloproteinase with Thrombospondin Motifs 4 (ADAMTS4), which degrades the four members of the lectican family (including NCAN and BCAN), has been implicated in Alzheimer’s disease." (PMID 38762535, 2024). "Reduction of the reelin level by ADAMTS-4 and ADAMTS-5-dependent degradation is associated with hyperphosphorylated tau protein, forming neurofibrillary tangles leading to Alzheimer’s disease." (PMID 38980840, 2024). "For example, the expression of ADAMTS-4 increases in pathological situations such as Alzheimer’s disease, ischemic stroke, amyotrophic lateral sclerosis, and spinal cord injury." (PMID 32150898, 2020).
breast cancer (6 papers, 2017 to 2024). A primary or metastatic malignant neoplasm involving the breast. "Using in vitro approaches and cultured breast cancer cell lines we demonstrate that Fibulin-2 is a better substrate for ADAMTS-5 than it is for ADAMTS-4." (PMID 28099917, 2017). "Taking into account previous results showing that ADAMTS-5 induces more significant differences on breast cancer cells behavior than ADAMTS-4, we focused our further efforts on ADAMTS-5 through the examination of the effect of different conditioned media on normal mammary fibroblasts." (PMID 28099917, 2017). "To elucidate whether endogenous Fibulin-2 could also be degraded by these proteases, we carried out transfections only with plasmids containing the full-length cDNA for ADAMTS-4 or ADAMTS-5 into SK-BR-3 breast cancer cells, which endogenously express Fibulin-2." (PMID 28099917, 2017). "The interaction of ADAMTS-12 with fibulin-2 results in a blockade of the proteolytic degradation of fibulin-2 by ADAMTS4 and ADAMTS-5 and therefore, inhibition of the tumoral properties of breast cancer cells." (PMID 33996918, 2021). "In fact, fibulin-2 can be degraded by ADAMTS-4 and ADAMTS-5 under the same experimental conditions, which results in an increase of the tumoral properties of breast cancer cells." (PMID 33996918, 2021). "Whereas ADAMTS4 expression was significantly up-regulated in invasive breast cancer tissues and human glioma, our study showed that the expression of ADAMTS4 gene does not affect the OS of GC patients." (PMID 33851708, 2021). "Interestingly, the degradation of fibulin-2 by either ADAMTS-4 or ADAMTS-5 is blocked by the presence of ADAMTS-12 and seems to be a target for the protective role of the fibulin-2/ADAMTS-12 interaction in breast cancer." (PMID 31508361, 2019).
glioma (6 papers, 2020 to 2023). A benign or malignant brain and spinal cord tumor that arises from glial cells (astrocytes, oligodendrocytes, ependymal cells). "For instance, brevican cleavage by ADAMTSs has been associated to progression of the gliomas, and an increased expression at both RNA and protein levels of ADAMTS-4 and ADAMTS-5 has been detected in glioblastoma, the most aggressive form of glioma." (PMID 33804223, 2021). "It has been proven that ADAM12, ADAMTS4 and 5 are implicated in the proliferation and invasion of glioma cells." (PMID 34638718, 2021). "Brevican promotes glioma cell motility through the upregulation of integrins and proteolytic cleavage by ADAMTS4." (PMID 37174618, 2023). "Using RT-PCR the authors proved that selected gliomas express ADAMTS4 and -5 when grown in situ, while GBM samples demonstrated the highest expression of these proteins, implicating these factors in malignancy." (PMID 34638718, 2021). "Moreover, ADAMTS4 mRNA is expressed by glioma cell lines with invasive properties and the cleavage of brevican by this enzyme is closely associated with the invasiveness of brain tumors." (PMID 34638718, 2021). "Other studies have examined the elevated expression of ADAMTS4 and ADAMTS5 (a disintegrin and metalloproteinase with thrombospondin motifs 4 and 5) in glioma samples on the mRNA and protein levels." (PMID 34638718, 2021). "However, other ADAMs with thrombospondin motifs (ADAMTS4, ADAMTS5) positively impacted the proliferation of glioma cells in vitro and potentially promoted their invasion by cleavage of brevican, a major component of brain tissue." (PMID 32346064, 2020).
rheumatoid arthritis (6 papers, 2014 to 2025). A chronic, systemic autoimmune disorder characterized by inflammation in the synovial membranes and articular surfaces. "In contrast, the elevated levels of soluble Sema4D protein in rheumatoid arthritis are not due to increased Sema4D mRNA expression but are driven by a disintegrin and metalloproteinase with thrombospondin motif 4 (ADAMTS4)-mediated proteolytic cleavage of membrane-bound Sema4D." (PMID 40507881, 2025).
glioblastoma (5 papers, 2006 to 2024). The most malignant astrocytic tumor (WHO grade IV). "In human glioblastomas, secretory proteases, such as ADAMTS4 and ADAMTS5, are expressed at the mRNA and protein levels in considerable amounts." (PMID 36980765, 2023). "In contrast, ADAMTS-4 (aggrecanase-1) and TS-5 (aggrecanase-2) are upregulated in glioblastomas (GBMs), with a possible role in increased degradation of brevican thereby increasing invasive potential." (PMID 16570050, 2006). "The authors concluded that ADAMTS4 and 5 are upregulated in proliferating glioblastoma cells and these proteases may promote their invasive potential." (PMID 34638718, 2021). "In addition, the levels of ADAMTS4 and 5 were more elevated in solid GBM tumor samples in situ than in cultivated glioblastoma cells." (PMID 34638718, 2021).
melanoma (5 papers, 2012 to 2024). A malignant, usually aggressive tumor composed of atypical, neoplastic melanocytes. "Rao et al20 further analyzed differential functions of different catalytic fragments of ADAMTS4 in the melanoma growth and angiogenesis." (PMID 31663692, 2019). "Using a syngeneic mouse tumor implant melanoma model, we demonstrated that catalytically-active full-length ADAMTS4 promoted melanoma tumor growth." (PMID 24213506, 2012). "Other group has demonstrated that full-length ADAMTS 4 promoted melanoma tumor growth." (PMID 26916548, 2016). "Indeed, it resulted quite appealing the fact that such positive association did occur with high expression of other ADAMTS proteases (ADAMTS2, ADAMTS4, ADAMTS5, ADAMTS9, ADAMTS12 and ADAMTS14) that definitively implied a key role of these proteases during melanoma progression." (PMID 32230715, 2020).
abdominal aortic aneurysm (4 papers, 2020 to 2023). Enlargement and ballooning of the vessel that supplies arterial blood to the abdomen, pelvis and legs. "The ADAMTS4-specific molecular magnetic resonance (MR) probe showed potential to predict abdominal aortic aneurysm (AAA) formation and rupture in a murine model." (PMID 37853734, 2023). "Studies have reported that miR-126a-5p reduces the occurrence of abdominal aortic aneurysm by inhibiting the expression of ADAMTS-4." (PMID 34055198, 2021). "miR-126a-5p-ADAMTS-4 is a potential therapeutic target for abdominal aortic aneurysm development." (PMID 36555554, 2022).